MUC1 (mucin 1, cell surface associated)
Diseases named in the same sentence as MUC1 in open-access papers (continued):
Sharing a sentence is not in itself a finding about the gene and the disease.
tumor (continued). "First, membranous localisation of MUC1 - as opposed to cytoplasmic localisation or total loss of expression - is an indicator of a more differentiated tumour." (PMID 25986064, 2015). "As data suggest that engagement of MGL in the absence of TLR triggering may lead to anergy, the binding of MUC1-STn to MGL may be in part responsible for some of the characteristics of STn expressing tumours." (PMID 25951175, 2015). "Furthermore, these vaccinations conferred protection to these mice when they were challenged with MUC1-expressing tumor cells." (PMID 26133558, 2015). "We incorporated a per-glycosylated MUC1 epitope (GVT*S*APDT*RPAPGS*T*APPAH), whereby all possible glycosylation sites were occupied with TACAs (indicated by asterisks), in order to maximize the potential recognition of glycopeptide tumor-associated epitopes." (PMID 26557640, 2015). "The human T-cell lines generated using these MUC1 agonist epitopes were more efficient than those generated with the corresponding native epitopes in terms of antigen-specific interferon (IFN)–γ production and lysis of tumor cells endogenously expressing native MUC1." (PMID 26374823, 2015). "Upregulation of TAAs such as CEA and MUC-1 in tumor cells may also increase the efficiency of immune surveillance." (PMID 26579226, 2015). "Given that CIN85 had previously been reported to associate with Cbl, which was shown to be necessary for the CIN85-mediated regulation of intracellular signaling, we examined whether Cbl might also be in the MUC1/CIN85 complex in tumor cells." (PMID 25675408, 2015). "KL-6 mucin is a type of MUC1 mucin that may play an important role in unfavorable tumor behaviors, including the invasion and metastasis of carcinoma of the ampulla of Vater." (PMID 25435926, 2015). "MUC1 Abs may control hematogenic tumor dissemination and outgrowth by aiding in the destruction of circulating or established MUC1-expressing tumor cells." (PMID 26133558, 2015). "Some studies show that overexpression of MUC1 is associated with better tumor behavior, absence of regional recurrence, and distant metastasis, but others demonstrate the opposite." (PMID 26693201, 2015). "However, the considerable variability in the expression of MUC1 among normal and tumor samples as evidenced by different detection methods has made it challenging to use in clinical settings." (PMID 26492273, 2015). "The present study shows MUC1 can be used for selective tumor targeting in vivo." (PMID 25815753, 2015). "However, the considerable variability in the expression of parental MUC1 among normal and tumor samples make it challenging to use it in clinical settings." (PMID 26492273, 2015). "This weak immunogenicity may due to the conformational disparities between the conjugated peptide and that of tumor-expressed MUC1." (PMID 26417929, 2015). "Moreover, pharmacological reduction of JNK activity not only shifted Smad3 signaling from oncogenesis to tumor-suppression but also inhibited cell proliferation in MUC1-overexpressing HCC cells." (PMID 25714018, 2015). "However, the considerable variability in MUC1 expression among tumor and normal samples has made it difficult to be used as a reliable clinical biomarker." (PMID 26492273, 2015). "As engagement of MGL in the absence of TLR triggering may lead to anergy, the binding of MUC1-STn to MGL may be in part responsible for some of the characteristics of STn expressing tumours." (PMID 25951175, 2015). "Since subcellular localisation of certain MUC1 isoforms has been associated with tumour cell aggressiveness and cancer prognosis, this relationship was also studied using the antibody PankoMab-GEXTM, which detects a tumour-associated epitope of MUC1 (TA-MUC1)." (PMID 25986064, 2015).
tumor (continued). "Moreover, the epithelial marker CA19.9 and MUC1 stained only part of the tumour suggesting that there are two separate and discrete albeit mixed components." (PMID 26589730, 2015). "Interestingly, Siglec-9 binding to MUC1 expressing tumor cells was shown to induce recruitment of β-catenin in tumor cells resulting in promotion of cell growth in vitro." (PMID 24592356, 2014). "MUC1 is a membrane-anchored mucin and its cytoplasmic tail (CT) can interact with many signaling pathways and act as a co-transcription factor to activate genes involved in tumor progression and metastasis." (PMID 24504508, 2014). "The first cloned mucin, MUC1, is an important human tumor antigen, ranking second after WT1." (PMID 24722639, 2014). "Furthermore, these changes trigger humoral immune responses, most likely due to the release of MUC1 from tumor cell surface followed by expansion of MUC1-specific B cells in tumor draining lymph nodes." (PMID 25078979, 2014). "Some studies have reported that serum levels of MUC1 (mucin 1, also called KL-6) and vascular endothelial growth factor (VEGF) are associated with tumor response, progression-free survival (PFS) and overall survival (OS) in NSCLC patients treated with EGFR-TKIs." (PMID 25410981, 2014). "In tumor cells, MUC1 distributes on all surfaces of the cells." (PMID 26344745, 2014). "Additional studies are currently being carried out in order to determine whether Pt12 with anti-MUC1 retains its activity in other tumor cell lines." (PMID 24639126, 2014). "In addition to their direct anti-tumor therapeutic potential, these antibodies can improve the selection criteria of MM patients aimed to be treated with the ImMucin anti-MUC1 SP therapeutic vaccine." (PMID 24416403, 2014). "More general tumor antigens, like MUC-1, AKAP-4, and NY-ESO-1, can also be found in PCa and might be candidates for immunotherapeutic interventions." (PMID 24834066, 2014). "Using triple transgenic MUC1KrasPten mice we show for the first time that concomitant activation of oncogenic Kras and deletion of Pten tumor suppressor throughout the female mouse genital tract consistently triggers MUC1 positive epithelial tumors with endometrioid histology." (PMID 25078979, 2014). "We also revealed that MUC1 expression was predominantly at the surface of tumor clusters." (PMID 25109922, 2014). "Moreover, the detection of MUC1 has been linked to the simultaneous expression of multiple angiogenic factors (as VEGF) and with an aggressive tumour behaviour." (PMID 24625834, 2014). "In fact, MUC1-CT is also considered as a part of the Wnt/β-catenin signaling pathway, which activation is associated to epithelial-mesenchymal transition (EMT), proliferation, migration and invasion in tumor context." (PMID 24504508, 2014). "Thus, compared with many other human neoplasms, MUC1 expression seems to be of little significance in SBC." (PMID 24722639, 2014). "Finally, compared to MDSCs from B16 Neo-tumor-bearing mice, MDSCs from B16 MUC1 mice expressed significantly higher levels of iNOS and Arg-1." (PMID 24605110, 2014). "MUC1 expression was related to tumor location (high for oral side, p = 0.019), invasion depth (higher for deeper than pSS (pT3), p = 0.017), venous invasion (high for positive venous invasion, p = 0.038), and curability (high for non-curative resection, p = 0.007)." (PMID 24722639, 2014). "The H-score for MUC1 staining increased from grade 1 to grade 2 tumor." (PMID 24671186, 2014). "The translatability of antigen and tumor specificities of anti-MUC1 SP antibodies to functional immunotherapeutic potential was demonstrated by effective lysis of MUC1-expressing cells by R23IgG, SPmAb-2.1 and SPmAb-6, indicating their potential as anti-tumor effectors." (PMID 24416403, 2014). "Similarly, exposing LNCaP cells to abiraterone significantly improved their sensitivity to MUC1-specific CTL-mediated lysis compared to vehicle-treated tumor cells (P < 0.05)." (PMID 25344864, 2014).
tumor (continued). "Furthermore, an interaction between MUC1 on the surface of cancer cells and serum-localized galectin-3 promotes strong adhesion of tumor cells to the endothelial surface, thus promoting cancer cell metastasis." (PMID 24639126, 2014). "Similarly, depletion of soluble MUC-1 in tumor cell line supernatants abolished the anti-proliferative effect of these supernatants on T cells, and MUC-1 has therefore been identified as a target in PCa." (PMID 24834066, 2014). "Our findings indicate that MUC1 expression in the tumor plays a key role in maintaining the MDSCs in an immature and highly suppressive state and may partially account for the metastatic nature of MUC1+ PDA tumors." (PMID 24605110, 2014). "In the present study, immunohistochemical analyses of MUC1 by HMFG2 antibody revealed that in benign bladder urothelium, MUC1 expression was either restricted to umbrella cells which is observed in majority of the cases, or it forms a sheath over transitional epithelium as seen in rare cases." (PMID 24671186, 2014). "One such chimera Chi-29b composed of a mucin 1 (MUC1) aptamer (that targets tumor cell surface MUC1 protein) coupled to miR-29b was recently shown to inhibit the growth of epithelial ovarian carcinoma cells in vitro by inducing apoptosis in a dose-dependent manner." (PMID 26835673, 2013). "In addition, ex vivo targeting of macrophages or DCs with oxidized mannan-MUC1 and reinjection into mice, induces strong CTL responses and protects against MUC1 tumor challenge." (PMID 24228179, 2013). "Therefore, similarly to the in vitro data, these observations clearly indicate that CIN85 plays important roles in the promotion of tumor metastasis and growth and its activity is modulated by MUC1." (PMID 24072600, 2013). "Interestingly, tumor MUC1 differs from normal epithelial MUC1 in a similar conformational change induced by O-glycosylation at the threonine of the sequence PDTRP with either TF or Tn." (PMID 23888272, 2013). "Cancer patients with MUC1 expression profiles may exhibit a Th2-skewed cytokine profile within blood and tumor-infiltrating lymphocytes." (PMID 26343966, 2013). "Changes in MUC1 structure are also involved in a variety of malignant tumor biology progress." (PMID 23708102, 2013). "Recently it was found that several of the tumor-related glycoforms of carcinoembryonic antigen, and MUC1 might affect CLR signaling and DC differentiation." (PMID 26343966, 2013). "In addition, core 2 O-glycosylated MUC1 carrying poly-N-acetyllactoseamine extensions impairs NK receptor interaction with tumor cells and protects bladder tumor cells from NK-mediated attack." (PMID 24039759, 2013). "One of the more important glycan decorated tumor antigens is human mucin 1 protein (MUC1)." (PMID 26343966, 2013). "MUC1 can, thus, be considered as an “abnormal selfantigen” when its glycosylation status is modified in tumor cells and this is an interesting property that could be exploited in immunotherapy." (PMID 23509794, 2013). "MUC-1-specific T cell clones, generated by stimulation with this peptide, could lyse targets pulsed with native Muc-1 epitope as well as HLA-A2+ MUC-1+ human tumor cells in vitro." (PMID 23509731, 2013). "Moreover, we assessed the effects of TGF-β1 derived from DC/tumor on the induction of MUC1-specific CTLs." (PMID 23555011, 2013). "In addition to higher levels of MUC1 in tumors compared to normal cells, hypoglycosylation of VNTR is the most important characteristic of tumor MUC1." (PMID 24072600, 2013). "Immunization with the multicomponent vaccine led to significant reductions in tumor burden and weight when compared with treatment using either empty liposomes or immunization with a control vaccine that didn’t contain the MUC1 glycopeptide epitope or an unglycosylated multicomponent candidate." (PMID 26343966, 2013).
tumor (continued). "Furthermore, the analysis of immune infiltrates in human tumors has demonstrated a positive correlation between prognosis and presence of humoral response to pancreatic antigens (MUC-1 and mesothelin) or of tumor-infiltrating T cells." (PMID 23509731, 2013). "Rowse and colleagues compared tumor growth of MUC1+ tumors in TG or Wt mice." (PMID 23509794, 2013). ", have been successfully applied in MUC1 anti-tumor vaccines." (PMID 23015828, 2012). "Alternatively, growth of MUC1-positive tumor cells may be suppressed in B6 mice, whereas this suppression was absent in MUC1.Tg mice." (PMID 23028615, 2012). "Therefore, taking our findings into consideration, it is possible that immunization with MUC1 peptides and transplantation of MUC1-expressing tumor cells activate and induce the proliferation of MUC1-specific Treg cells." (PMID 23028615, 2012). "Furthermore, the number of tumor infiltrating Ki-67+ Treg cells normalized to tumor weights in MUC1.Tg mice was apparently greater than that in B6 mice, presumably due to the presence of MUC1 in the tumor microenvironment." (PMID 23028615, 2012). "However, the cleaved form of the MUC1 protein (MUC1*) has growth factor receptor-like activity on tumour cells and is detected in populations of pluripotent stem cells." (PMID 22454081, 2012). "Moreover, Apt-Dox retained the efficacy of doxorubicin against MUC1-positive tumor cells, but lowered the toxicity to MUC1-negative cells (P<0.01)." (PMID 22384115, 2012). "The immunogenicity of synthetic MUC1 glycopeptides bearing Tn or sialyl-Tn antigens have been studied in mouse models, while authentic glyco-epitopes expressed by tumor cells remain unclear." (PMID 23023583, 2012). "L-BLP25 is designed to induce cellular cytotoxicity towards MUC1 expressing tumor cells." (PMID 22494623, 2012). "We then considered whether the MUC1 cytoplasmic domain might be sufficient for tumor cell metastasis." (PMID 22586492, 2012). "CA 15–3 and CA 27.29 are available tumour marker assays for detecting MUC1." (PMID 23241107, 2012). "However, use of chaperone-based vaccines in experimental animals can lead to the “Holy Grail” of antigen-specific antitumor immunity and can overturn tolerance to tumor antigens such as MUC1." (PMID 23056925, 2012). "Suppression of anti-tumor immune response by IL-10 may allow the rapid tumor growth observed in MUC1.Tg mice." (PMID 23028615, 2012). "Moreover, the percentages of tumor infiltrating Teff cells in MUC1.Tg mice were smaller than those in B6 mice at this time point." (PMID 23028615, 2012). "Remarkably, overexpression of MUC1 in cancer cells correlated with tumor metastasis, poor prognosis, and resistance to chemotherapeutic agents, which suggest that MUC1 and c-Met might work together." (PMID 22962849, 2012). "Importantly, overexpression of MUC1, MUC4 and MUC5AC are associated with poor survival and serve as potential tumor markers for PC." (PMID 23102107, 2012). "Moreover, expression of MUC1.CD results in its nuclear localization and is sufficient for transcription of the metastatic gene signature and tumor cell metastasis." (PMID 22586492, 2012). "Furthermore, we were able to show, for the first time, that MUC1-specific peripheral tolerance operates in MUC1.Tg mice to support the tumor growth in vivo." (PMID 23028615, 2012). "Given that the MUC1 cytoplasmic domain is sufficient to enhance metastasis, our studies suggest that therapies targeting the MUC1 ectodomain on tumor cells may provide limited clinical benefit." (PMID 22586492, 2012). "Therefore, the enhanced growth of MUC1-expressing tumor cells in MUC1.Tg mice is likely due to the presence of MUC1-specific Treg cells." (PMID 23028615, 2012). "However, the weight of cecum induced by SL4-MUC1 cells was heavier when the cells were injected into MUC1.Tg mice than when they were injected into B6 mice, suggesting that the growth of MUC1-positive tumor cells was enhanced in MUC1.Tg mice." (PMID 23028615, 2012).
tumor (continued). "Therefore, we believe that our findings that MUC1-specific Treg cells suppress IL-2 production from MUC1-specific CD4+ T cells provide important information in tumor immunity." (PMID 23028615, 2012). "Such enhancement was a result of increased numbers of Treg cells in tumor tissues expressing MUC1." (PMID 23028615, 2012). "An Hsp70 vaccine derived from MC38 cells expressing the tumor antigen MUC1 was shown to trigger DC maturation and expression of costimulatory molecules and trigger CTL that could kill target tumor cells in an antigen- (MUC1-) specific manner." (PMID 23056925, 2012). "However, a significant correlation has been found between the histopathological grade of the tumour malignancy and MUC1 expression and between the histopathological grade of the tumour malignancy and the circulating CA 15–3 level." (PMID 22726603, 2012). "It is expressed on normal cells and so far we do not have the ability to distinguish between tumour-associated MUC1 and normal MUC1; the shed N-terminal subunit acting as a large pool to absorb the antibody." (PMID 23241107, 2012). "In this experimental system, we achieved to exclude the possible involvement of central tolerance, which was suggested to be the major mechanism to establish the tumor antigen-specific tolerance, because functional MUC1-specific T cells were transferred from B6 mice." (PMID 23028615, 2012). "The lack of progress in the development of a MUC1-based cancer vaccine may stem from some of the inherent properties of MUC1 protein such as variations in glycosylation patterns in tumour and non-tumour cells." (PMID 23166757, 2012). "MUC1 has also been reported to be a poor prognostic factor in various human neoplasms." (PMID 23152882, 2012). "The synthetic mimics of MUC1, described here, may be capable of directing T-cell responses against tumour cells expressing MUC1, leading to tumour cell killing." (PMID 23166757, 2012). "This should be combined with the knowledge of the role that the STn antigen plays in the function of the STn-expressing proteins, MUC1 and others and in overall tumor cell progression in order to identify potential synergistic solutions for treating STn-expressing carcinomas." (PMID 24970145, 2012). "Based on properties such as immunogenicity, tumour specificity, cellular localisation and expression levels, and percentage of patients with antigen positive cancer, MUC1 ranked second for prioritisation in a list of 75 previously characterised tumour antigens." (PMID 23166757, 2012). "Count rates per weight tissue (cps/g) determined in the well counter and calculation of tumour/foot ratio (foot serving as reference region) showed 131I-anti-MUC1 retention in 4 of the 5 mice (median 14 cps/g, range 1–109) and low tumour retention of 131I-anti-TNP (median 1 cps/g, range 1–6)." (PMID 21603241, 2011). "The anti-MUC1 scFv reacted with tumour cells in more than 80% of 228 tissue sections of mamma carcinoma samples, while showing very low reactivity with a large panel of non-tumour tissues." (PMID 21264246, 2011). "Future studies to link MUC-1 and sNDPK and possibly the P2 receptor may further our understanding of tumour cell-mediated angiogenesis." (PMID 21505453, 2011). "The specific binding of the scFv antibody to the VNTR region of tumour-associated MUC1 was confirmed by ELISA (data not shown) and immunoblot." (PMID 21264246, 2011). "In vivo studies have shown that MUC1 downregulation impacts tumor development." (PMID 22073229, 2011). "Additionally, also using Oncomine to search for the tumour grade and the prognostic impact, we found that all the marker genes except MUC1 were significant for prognosis in the calculation of this database." (PMID 21314937, 2011). "Furthermore, anti-MUC1 antibodies are capable of effecting tumor cell killing by antibody-dependent cell-mediated cytotoxicity." (PMID 24212946, 2011).